Y_RNA (Y RNA )
Gene: Miscellaneous RNA gene on chromosome 11 (2,372,638 to 2,372,750, forward strand). Ensembl gene ENSG00000199550.
Homologues: Orthologues: chimpanzee Y_RNA (100% identical), macaque Y_RNA (93% identical). Paralogues in human: RNY1 (91% identical), Y_RNA (88% identical), Y_RNA (87% identical), RNY1P11 (86% identical), Y_RNA (86% identical), Y_RNA (85% identical), Y_RNA (84% identical), Y_RNA (83% identical), RNY1P7 (82% identical), RNY1P8 (82% identical), Y_RNA (82% identical), Y_RNA (81% identical), and 96 more.